GZMB (granzyme B)
Diseases named in the same sentence as GZMB in open-access papers (continued):
Sharing a sentence is not in itself a finding about the gene and the disease.
tumor (continued). "A bispecific antibody against both PD-L1 and CD3 successfully connected T cells to PD-L1-expressing tumor cells, improved T cell cytotoxicity against multiple NSCLC-derived cell lines by releasing granzyme B and cytokines, and decreased tumor growth in mice." (PMID 36389699, 2022). "Cytotoxicity-related genes GNLY, NKG7, GZMB and GZMA were downregulated in both tumor-derived CD4+ and CD8+ T cells." (PMID 36506053, 2022). "In Precision Cut CRC Tumor Slice Cultures, treatment with LY6G6D/CD3 induced activation of tumor infiltrating T cells, measured by released inflammatory cytokines and granzyme B, only in LY6G6D-positive tumors." (PMID 36159851, 2022). "Another study on multiple tumors showed that vvDD-IL-23 can promote the expression and release of Th1 chemokines and some anti-tumor factors, which contained IFN-γ, as well as tumor necrosis factor-α (TNF-α), IL-2, perforin, and granzyme B (GzmB)." (PMID 36090998, 2022). "Strikingly, CD8High T cells showed a high expression of granzyme B and KLRD1 in all investigated tumour entities." (PMID 36504430, 2022). "CD8+ cells are critically important in direct killing of tumor cells via the induction of apoptosis and cytokine secretion [interferon (IFN)-γ, granzyme B]." (PMID 36518315, 2022). "The expression levels of other hub genes CTLA4, CXCL10, CCL5, CCl4, ICAM1, CXCL9, CD27, GZMB, FCGR2A, SELL, IDO1 in SKCM were higher than those in non-tumor skin tissues (P < 0.05), and the results were statistically significant." (PMID 35710862, 2022). "IHC analysis showed that the PGRN Ab-induced reduction of PanCK+ tissues was restored by co-treatment of CD8 depletion Ab, while increased tumor infiltration of CD8+ and granzyme B+ cells were prominently abrogated." (PMID 35013174, 2022). "Tumor biopsies were collected for detection of programmed cell death ligand 1, CD8, 4-1BB, perforin, and granzyme B, and gene expression analyzed by next-generation sequencing." (PMID 35983060, 2022). "GZMA and GZMB were previously reported to be specifically expressed in CD8+ T cells, indicating that PRRS is a signature involving not only tumor cells but also immune cells." (PMID 35990696, 2022). "d-MAPPS significantly increased the presence of tumor-infiltrated CD178-expressing and granzyme B-producing cytotoxic CD8+ T cells (CTLs; p < 0.001)." (PMID 35757015, 2022). "We found that cisplatin-pretreated tumor cells stimulate neutrophils which expressed higher levels of cytotoxic effectors, including TNF-α, GZMB, and ELANE, and pro-inflammatory cytokines, such as CCL2, CCL3, CXCL10, CXCL11, and IL12." (PMID 35784745, 2022). "Even though the tumor tissues had high P-AKT and Ki67 staining, IHC and FACS analyses showed persistent infiltration of CD8+ T and GZMb+ cells." (PMID 35013322, 2022). "Historically, CD8+ T cell–mediated killing is thought to occur predominantly via the perforin-granzyme B pathway, whereas CD4+ T cell–mediated killing is thought to rely on activation of the death receptor Fas on tumor cells by Fas ligand expressed on T cells." (PMID 36271507, 2022). "CD8+ T cells, which are a subtype of the cytotoxic T lymphocytes, contribute a lot to the antitumor activity through releasing of tumor cytokines such as INF-γ, perforin and granzyme B." (PMID 35739510, 2022). "The combination treatment enhanced the expression of CD69 in the tumor-infiltrating CD8+ T cells, increased tumoral GzmB, and decreased tumor cell proliferation." (PMID 35380995, 2022). "Then, progranulin antibody therapy increases levels of granzyme B, TNF, IFN-γ, and CD8+ T cells, reviving CD8+ T cell anti-tumor cytotoxicity." (PMID 36300110, 2022). "Aside from caspases, granzyme A has been reported to cleave GSDMB in lymphocytes, and granzyme B was reported to directly cleave GSDME in tumor cells, ultimately contributing to tumor suppression by invoking pyroptosis." (PMID 36093182, 2022).
tumor (continued). "Consistent with our results in the database, GZMA, GZMB, IL18, and IRF1 were decreased in tumor tissues than normal tissues." (PMID 35464869, 2022). "Like ZA, this molecule has been shown to enhance the sensitivity of tumour cells to Vδ2 killing and enhances Vδ2 production of IFN-γ, TNF, granzyme B and perforin." (PMID 36713444, 2022). "This study identified that expression of CD8, GZMB and CD68 within 25 μm of tumour cells at the tumour centre were strongly predictive of survival." (PMID 36114487, 2022). "T cells or NK cells in the peripheral blood showed a pattern similar to that of tumor samples, indicating that Q702 treatment increased the proportion of IFN-γ-producing CD4 T and NK cells and granzyme B+ CD8 T cells." (PMID 36230744, 2022). "We identified regions within tumor samples in which T cells co-expressed CD4 and GZMB, and tumor cells co-expressed pan-CK and HLA-DR." (PMID 35831288, 2022). "A significant anti-tumor effect was observed in the irradiated and abscopal tumors, thus we next examined the immune microenvironment including CTL (CD8+, Granzyme B+ (GzmB+) in CD45+) and Treg (CD4+, FoxP3+ in CD45+)." (PMID 35565217, 2022). "Patients that respond to PD-1 blockade also exhibited increased expression of STAT1, CXCL9, CXCL10, GZMB, CD8A, and CD8B, which is consistent with our observation in tumor model with IFNα-MSC treatment." (PMID 35145233, 2022). "After the recognition of antigens or other stress-induced molecules expressed on tumor cells by TCR or NKR, γδT cells can mediate the direct tumor lysis by producing granzyme B, perforin, TNF-α and IFN-γ." (PMID 35747139, 2022). "A stepwise increase in the expression of all of these molecules was observed over time, such that CD8 T cells retained within the tumor for at least 72 h robustly expressed PD-1, LAG-3, CD39, and the highest level of Granzyme B." (PMID 35472220, 2022). "Clinical-pathological evaluations, survival at follow-up, immunophenotyping of leukocytes in peripheral blood and tumours, and immunohistochemical evaluation of CD4+, granzyme B, perforin and FAS-L were performed." (PMID 35512031, 2022). "Granzyme B is a serine protease released by active NK cells and CD8+ cytotoxic T-cells along with the pore-forming protein perforin to induce apoptosis in tumours providing information on tumouricidal activity." (PMID 35057046, 2022). "Reduces tumor weight, increases the levels of IFN-γ, TNF-α, GZMB and the expression of CLCA3, TFF3, AGR2, Zg16, Pla2g10, Guca2a." (PMID 35548468, 2022). "A positive correlation between GSDMD and CD8A, GZMB, and IFNG expression in CTLs was also seen in many other tumor types and in 30 primary tumor samples from patients with NSCLC, further confirming the associations seen from TCGA." (PMID 34429144, 2021). "CD8+ T cells from Hepa1-6 shGOLM1 tumor exhibited low PD-1 and TIM-3 expression relative to Hepa1-6 shNT tumor, with increased effector cytokines, IFN-γ and GZMB." (PMID 34795203, 2021). "NK cells produce less granzyme B and perforin as well as reduce their surface expression of NKG2D further limiting their effectiveness at tumor cell clearance." (PMID 34832522, 2021). "Then, we found tumor-infiltrating CD38+ CD8+ T cells and CD38− CD8+ T cells both were decreased in the secretion of Granzyme B compared with normal tissue and peripheral blood." (PMID 33934206, 2021). "The GZMB/CD8A ratio can reflect the degree of immune cytotoxicity and cytotoxic T lymphocyte infiltration, which can be used to predict the response of tumor genes to immune cells." (PMID 34394706, 2021). "In the context of liver TME, tumor-derived MAIT cells secreted less IFN-γ, IL-17, and granzyme B, perforin, but they secreted more IL-8, which promotes tumor angiogenesis and progression." (PMID 34071188, 2021). "The post-treatment tumor tissues of this patient showed an increased infiltration with T cells (CD3+, CD8+), CD20+ B cells, and immune cells expressing Granzyme B and PD-1." (PMID 34737281, 2021).
tumor (continued). "In a murine tumor model, IL-2 secreted from tumor-resident CD4+ T cells increased CD8+ T cell proliferation and granzyme B expression." (PMID 34012451, 2021). "At the same time, the percentage of CD4 CTLs (CD4+Thpok−) and the expression of the CTL cytokine Granzyme B in CD4+ T cells were notably increased after RFA and cryo-thermal therapy compared to that in tumor-bearing mice." (PMID 34576115, 2021). "The tumor compartment of primary samples had significantly higher expression of immune cell markers CD45, CD8, ARG1, GZMB, BIM, BCL2, showing brain metastases have very few immune cells infiltrating in the tumor epithelium." (PMID 34838031, 2021). "In MMTV-Erbb2 breast, MC38 colon, and B16-F10 melanoma tumor models, CDK4/6 inhibition led to a decrease in total numbers of CD3+ tumor infiltrating T cells, encompassing CD8+ T cells and Granzyme B+ and IFNγ+ cells." (PMID 34025662, 2021). "We found that in PRMT5 knockdown tumor microenvironment, the expression of IFN-γ and TNF-α in CD4+ T and CD8+ T cells were increased, and the expression of granzyme B in CD8+ T cells was also upregulated." (PMID 34522232, 2021). "Hypoxic cytotoxic T lymphocytes when transferred in vivo were reported to package more granzyme B and be more efficient in controlling tumor growth and improve animal survival in a B16-OVA tumor model." (PMID 34202979, 2021). "The percentage of activated CTL within the tumor represented a prognostic indicator, as patients with a higher intra-tumoral percentage of CD8 + Granzyme B+ cells had the better outcome." (PMID 33947438, 2021). "Upregulation of NPTX2 in cold tumor negatively correlated with the expression of CD8A, GZMB, and IFNG, and knockdown of NPTX2 increased the production of CCL4." (PMID 34258887, 2021). "When PD-1 inhibitor antibodies were combined with anti-HER2 CAR T-cells, significant tumor volume reduction was seen and levels of IFN-γ and granzyme B increased, indicating improved immune response." (PMID 33442419, 2021). "Tumor cells were positive for CD3 and granzyme B. CD30 was diffusely positive and ALK was also diffusely expressed in cytoplasm and nuclei." (PMID 34072328, 2021). "Immunohistochemistry staining showed that granzyme B+ and CD8+ T cells in the tumor tissues were significantly increased in the combination group." (PMID 34858816, 2021). "In our study, we also found that tumor-infiltrating CD38+ CD8+ T cells and CD38− CD8+ T cells have significantly decreased of IFN-γ and Granzyme B secretion compared to adjacent normal tissues." (PMID 33934206, 2021). "Analysis of tumor-infiltrating lymphocytes showed decreased CD8+ T-cell infiltration and IFN-γ or Granzyme B production in Malt1−/− mice." (PMID 33963274, 2021). "We demonstrated cytotoxic granule release of LA/DC-CTLs or LA/DC-NK cells and cytotoxicity against tumour cells and microtissue blocks via the predominant IFN-γ/perforin/granzyme B cell death pathway." (PMID 33910591, 2021). "Whiteside and co-Workers affirm that once exposed Treg with tumour Exo, these immunosuppressive cells show enhanced suppressive functions and exhibited a greater expression of IL-10, TGF-β, Fas Ligand, CTLA4, granzyme B (GrB) and perforin." (PMID 34943819, 2021). "While enhanced secretion of granulysin and granzyme B directly account for increased tumor lysis, IFN-γ and TNF-α stimulate the endogenous immune system and indirectly enhance anti-tumor activity." (PMID 33807875, 2021). "One interesting phenomenon is that surgical treatment of tumor-bearing mice upregulates the lipid content of splenic NK cells with high CD36 and low GzmB expression." (PMID 34742349, 2021). "Both CD8+ T and NK cells are critical executors that mediate tumor cell apoptosis through secretion of granzyme-B and IFN-γ in immunotherapy modulating tumor regression." (PMID 33918641, 2021).
tumor (continued). "In these mice received low-dose decitabine-pretreated CD4+ T cells, the expression levels of cytotoxic marker granzyme B and TNF-α were also upregulated in tumor infiltrated CD4+ T cells." (PMID 33791306, 2021). "As a result, similar to human tumors, the infiltrating T cells in Pan02 tumors are suppressed, lack effector functions, such as granzyme B secretion and IFN-γ production, and often fail to elicit effective anti-tumor responses." (PMID 33503832, 2021). "GzmB and perforin were also reported to be expressed in FOXP3+ Tregs in mice, in particular in tumor models, but circulating human FOXP3+ Tregs express only very low levels of GzmB." (PMID 34910301, 2021). "Globally, this assay can provide insight on how CAR T cells are acting within a solid tumor setting and how the heterogeneity effector genes such as GZMB and IFNγ of the CAR T cell population affects the reduction in tumor size." (PMID 34155235, 2021). "We also detected higher levels of infiltrating CD8 T lymphocytes with higher granzyme B expression in the YUMM1.7-CM generated tumors and most importantly, suppression of tumor growth in response to anti-CTLA-4/anti-PD-1 checkpoint blockade regimen." (PMID 34295826, 2021). "GZMB, PRF1 and IFNγ are activation markers and PD-1 is the exhaustion marker of CD8+ T cells, whereas GZMB and PRF1 are major hydrolytic enzymes leading to tumor apoptosis." (PMID 34680466, 2021). "Immunohistochemistry (IHC) highlighted tumor cells as strongly positive for CD3, CD56, CD5, CD2, CD8, CD4, CD43, T-cell restricted intracellular antigen 1 (TIA-1) and granzyme B. The proliferation index, measured by Ki-67 expression was high with 60%." (PMID 33546043, 2021). "BT942 treatment resulted in remarkable increase in CD45+, CD3+, CD8+, CD8+ granzyme B+, CD8+Ki67+, CD4+, CD4+Teff, CD4+Teff granzyme B+ and CD4+Teff Ki67+ T cell percentage in MC38 tumor." (PMID 34824364, 2021). "It has been found that NK cells from obese mice are less sensitive to tumor cells due to inhibition of their cytotoxic activity and decreased production of IFN-γ, granzyme B, and perforin." (PMID 34768814, 2021). "oe-lnc-SNHG10 exo induced tumor growth and upregulated INHBC expression in mice and downregulated the expression of perforin, granzyme B, and NK1.1 in tumor tissues." (PMID 34641864, 2021). "In this same cohort, tissue samples with high RIPK3 expression show strong reactivity to anti-CD8 and anti-Granzyme B antibodies, implicating the involvement of RIPK3 in regulating the anti-tumor microenvironment." (PMID 34419074, 2021). "Higher percentages of CD8+ T cells isolated from Six1−/− tumor tissues expressed effector T cell activation markers such as IFN-γ and GZMB, which was confirmed by an IFN-γ ELISpot assay." (PMID 34782761, 2021). "Mechanistically, tumour αV regulates CD8 T cell recruitment, induces CD103 expression on activated CD8+ T cells and promotes their differentiation to granzyme B-producing CD103+CD69+ resident memory T cells via autocrine TGF-β signalling." (PMID 34471106, 2021). "Increased in vivo efficacy by A2AR-knockdown CAR T cells was associated with increased expression of effector-related genes in tumor-infiltrating CD8+NGFR+ CAR T cells such as IFNγ, TNF, IRF4, and Granzyme B." (PMID 34050151, 2021). "The infiltration of multifunctional (IFN-γ+GzmB+) CD8+ T cells, which have previously been shown to be cytolytic, into tumor was also greatly increased following PRGN-2009 treatment (48.4%) compared with PBS control (0%)." (PMID 33651712, 2021). "Umblical cord blood (UCB)-derived CAR-NK cells, showing an immature phenotype with a reduced expression of CD16, perforin, and granzyme B, but an increased expression of an inhibitory molecule, NKG2A, reduced the cytotoxicity against tumor cells." (PMID 34072645, 2021).
tumor (continued). "For analyzing ESR2 expression level versus T cell infiltration in each tumor, the total expression of CD4, CD8α, GZMB (log2 counts per million) was used to assess the infiltration of cytotoxic T-lymphocytes, and correlations were computed vs ESR2 expression." (PMID 33462142, 2021). "We have evaluated [18F]AlF-mNOTA-GZP, a radiolabeled peptide targeting granzyme B, to stratify response to ICIs in a HEPA 1-tumours, a syngeneic model of HCC." (PMID 35936114, 2021). "Tumor and spleen infiltrating CD3+ and CD8+ T cells, T-cell cytotoxicity makers GzmB+ and IFN-γ+, T-cell exhausted markers including TIM-3 and PD-1 were further identified by flow cytometry." (PMID 34718325, 2021). "Human CD2high pDCs infiltrated in TME express high levels of granzyme B, TRAIL and lysozyme, which limit proliferation of tumor cells and mediate contact-dependent killing of tumor cells." (PMID 34359674, 2021). "In a separate patient cohort (n = 11), T cells were classified using CD3, CD4, CD8, FoxP3, and granzyme B in paired PBMC and single cell suspensions of tumor samples." (PMID 34926643, 2021). "The tumor-infiltrating CD3+ CD+ T cells and CD38− CD+ T cells have significantly decreased secretion of IFN-γ and Granzyme B compared to paired adjacent normal tissues." (PMID 33934206, 2021). "In general, we discovered that most tumor infiltrating immune cells localized in the central region of the tumor, including CD4+ GzmB+ T cells." (PMID 34631551, 2021). "Corresponding to the altered TAM polarization in Maoa KO mice, tumor-infiltrating CD8+ T cells in these mice showed enhanced activation (i.e., increased production of Granzyme B)." (PMID 34112755, 2021). "Ex vivo analyses on tumor masses with comparable volumes were performed to evaluate the expression levels of HER-2, perforins/granzyme B and cell-cycle checkpoint regulators." (PMID 33800754, 2021). "In contrast, there were significantly more cytotoxic markers, such as GZMB, in exhausted CD8+ T cells at the edge of the tumor than at the core of the tumor." (PMID 34513820, 2021). "The exosomal protein levels of PFN, GzmA, GzmB, and GNLY are deciding factors for the tumor lysis ability of NK-EVs." (PMID 33808645, 2021). "We found that the tumor-infiltrating TRM-like subset expressed a high level of GZMB, whereas other subsets showed much lower expression, indicating the TRM-like subset as a major cytolytic lymphocyte in the tumor." (PMID 34663810, 2021). "This outcome, and the observation that the hexatherapy regimen increased granzyme B and IFN-γ production, indicate that the hexatherapy regimen converted the 4T1 tumor into the infiltrated-inflamed phenotype." (PMID 33602696, 2021). "In our results indicated the combination group presented significantly higher expression of granzyme-B and apoptotic proteins (BAX and cleaved-caspase-3) in CT-26 or B16-F10 tumor tissues compared to hIL15-ABD or anti-PD-L1 therapy." (PMID 33918641, 2021). "I-E TIMEs are considered to be immunologically ‘cold’ since CTLs in them have low expression of activation markers granzyme B and IFNG and they have poor CTL infiltration into the tumour core." (PMID 34771746, 2021). "As shown in the volcano plot, SU decreased GZMB expression and upregulated genes related to inflammatory activation (FOS, JUN, NFKBIA, DUSP2, JAK1, PIM1), tumor immunity (CD47, PCBP2, EIF5A, PDIA3, EGR1), and DNA damage (H2AFX, DDIT3, GADD45B)." (PMID 34824394, 2021). "Tumor specificity can also be increased by equipping CAR T cells with COVERT molecules (Cytoplasmic oncoprotein verifier and response trigger), which are granzyme B molecules that are fused to an N-terminal inhibitory peptide sequence." (PMID 34885176, 2021). "One reason for this low response rate is low tumor immunogenicity, marked by diminished infiltration of CD8+ T-cells and cytotoxic markers, such as IFN-γ and granzyme b, at the primary tumor site." (PMID 33668795, 2021).